PAX3 (paired box 3)
Diseases named in the same sentence as PAX3 in open-access papers (continued):
Sharing a sentence is not in itself a finding about the gene and the disease.
melanoma (continued). "Early studies indicated that PAX3 was capable of transactivating the promoter of MITF, a transcription factor involved in melanocyte differentiation and an oncogene associated with melanoma cell survival." (PMID 38473380, 2024). "For example, in melanoma cells, Ets-1 cooperates with PAX3 to increase the transcription of the c-Met gene." (PMID 39468027, 2024). "In melanomas as well as in benign melanocytic nevi, PAX3 expression can be detected and has been used as a biomarker." (PMID 38473380, 2024). "In melanoma cell lines, for example, the inhibition of PAX3 induces apoptosis and markedly impedes cell survival." (PMID 38928435, 2024). "PAX3 expression increased upon melanoma cell injection and decreased upon MC extract administration." (PMID 39684511, 2024). "First, we investigated the transcriptional activity of PAX3 or TBX5 in the melanoma cell lines SBcl2, WM1366 and MV3 using reporter gene assays." (PMID 38388496, 2024). "For example, the PAX3/MITF/PGC1α axis promotes MAPKi tolerance in a subset of melanoma cells through a mitochondria-mediated metabolic shift." (PMID 37616051, 2023). "Uveal melanoma-specific hits were enriched for YREs present in the loci of three master regulators of gene expression in the melanocytic lineage and melanoma: PAX3, SOX10 and MITF." (PMID 37400441, 2023). "In melanoma, the regulatory activity of YAP is able to regulate the phenotype differentiation of melanoma cells through YAP/PAX3/MITF or YAP/TEAD/SMAD transcription in sensing the stiffness of the ECM." (PMID 36233186, 2022). "Taken together, these results indicate that DUSP4 selectively controls cell viability in BRAF-mutant melanoma cells by functioning as a rheostat for ERK signaling which in turn drives the PAX3-MITF pathway." (PMID 35580987, 2022). "PAX3 expression is controlled in melanoma by PI3K signaling, which has been implicated in both melanomagenesis and senescence bypass through inactivation or loss of PTEN, an inhibitor of PI3K, or via activating mutations in PI3K itself." (PMID 34819350, 2021). "Another early study showed that a pan-PKC inhibitor, Gö 6983, blocked WNT5A-mediated melanoma dedifferentiation in vitro, with increased expression of PAX3 and melan-A." (PMID 34604096, 2021). "A stiffer ECM with increased collagen levels induces proliferation and differentiation of melanoma cells via Yes1-associated transcriptional regulator (YAP) and PAX3, which interact and thereby promote MITF expression." (PMID 34071193, 2021). "Gene expression analysis of five melanoma-associated genes, including MLANA, TYR, MAGEA3, ABCB5 and PAX3, showed that at least one transcript was detected in 18 out of 43 samples analysed (42%)." (PMID 32037400, 2020). "Expression of both genes has been shown to increase in melanoma, while siRNA-mediated PAX3 downmodulation significantly decreased the expression of BCL2L1 in several melanoma cell lines." (PMID 32466509, 2020). "Mutating (P2mut) or deleting (∆55) P2 also completely abolished the ability of PAX3 to stimulate transcription from the MITF promoter in melanoma cells." (PMID 30277012, 2019). "Using RNAi we confirmed previous findings that both, BRN2 and PAX3 contribute to MITF expression in melanoma cells." (PMID 30277012, 2019). "This was independent of the BRAF/NRAS mutation status, and suggests that PAX3 induced MITF expression is an inherent melanocyte lineage trait that is conserved in melanoma independently of the genetic background." (PMID 30277012, 2019). "The dependence of MITF upregulation on low ERK activity suggests that in melanomas in which the PAX3/BRN2 rheostat is intact, MITF will be upregulated on treatment with MAPKi." (PMID 30277012, 2019). "The results showed that overexpression of PAX3 in EOC tissues was significantly associated with poor prognosis, as reported in previous studies on melanoma, glioma, gastric carcinoma, and breast cancer." (PMID 31823759, 2019).
melanoma (continued). "Together, these data indicate that YAP regulates MITF expression in melanoma cells in a PAX3-dependent manner." (PMID 29545604, 2018). "In differentiated melanocytes, TGFβ can reduce MITF through the suppression of PAX3, and we have recently shown that this regulatory link is preserved in melanoma cells." (PMID 29545604, 2018). "For instance, Pax3 SiRNA was transfected in to human metastatic melanoma to elaborate the function of Pax3 in melanoma growth and survival." (PMID 30469474, 2018). "We demonstrate that collagen stiffness induces melanoma differentiation through a YAP/PAX3/MITF axis and show that in melanoma patients increased collagen abundance correlates with nuclear YAP localization." (PMID 29545604, 2018). "The results demonstrate that SEE prevents the activation of the α-MSH−MITF−TYR axis by attenuating Pax3-mediated MITF expression in B16F10 melanoma cells." (PMID 29865165, 2018). "Several studies have demonstrated that Pax3 is frequently expressed in normal melanocytes and aggregated melanomas." (PMID 30469474, 2018). "Both members of the paired box type homeobox transcription factor family, Pax3 and Pax7, are involved in neurogenesis, cardiogenesis, melanoma cell pathophysiology, and myogenesis during development." (PMID 28638414, 2017). "Recent reports have suggested that melanoma cells switch back to the embryogenetic program initiated during neural crest formation by means of several factors as PAX3 and MITF." (PMID 29156734, 2017). "As the melanoma invasiveness intensifies, CMCs exhibit high amount of PAX3 transcripts which leads to a reduction in pigmentation and mitotic rate as well as an increase in cellular migration." (PMID 29156734, 2017). "In context with our finding that MYSM1 bound to the c-MET promoter region in close vicinity to PAX3 in melanoma cells, our data indicate that MYSM1 is an epigenetic regulator of melanoma growth and potentially promising new target for tumor therapy." (PMID 28978033, 2017). "PAX3 is also expressed in nevi, primary melanoma as well as metastatic melanoma at various concentrations." (PMID 27428965, 2016). "It has been shown that PAX3 is expressed in melanoma tissues, cell lines and circulating melanoma cells as well as normal skin melanocytes and melanocytic lesions." (PMID 27428965, 2016). "As a member of PAX gene family, PAX3 has been found to be correlated with oncogenesis, and is upregulated and highly expressed in glioblastomas, neuroblastomas, melanomas, rhabdomyosarcomas, Ewing sarcomas and gastric cancers." (PMID 27458157, 2016). "Sox10, Pax3 and Mitf genes are key regulators of melanocyte development, and regulate Met expression in melanocytes and melanoma cells." (PMID 27683122, 2016). "We also assessed melanoma cell survival in response to the drug library and set a threshold at the effect on survival induced by RNAi-mediated depletion of PAX3 or MITF, respectively." (PMID 26977879, 2016). "The suppressor function of SKI is maintained in melanoma, where its overexpression led to a reduction and its depletion to an increase in PAX3 and MITF expression." (PMID 26977879, 2016). "While we saw no striking differences in post-translational modifications of PAX3 isoforms, we did observe differences in alternate PAX3 transcript expression profiles and in translation of mRNA between melanocytes and melanoma cells." (PMID 25880082, 2015). "To further confirm differential target gene regulation we silenced PAX3 in several primary melanocytes and melanoma cell lines, and analysed changes in the target gene expression." (PMID 25880082, 2015). "To further discern the roles of PAX3 in melanocyte and melanoma cells, we have analysed the correlation between PAX3 and MITF and BRN2." (PMID 25880082, 2015). "On the other hand, treatment of non‐resistant melanoma cells with TGFβ suppresses PAX3 and MITF expression and sensitizes melanoma cells to MEK inhibition." (PMID 25818589, 2015).
melanoma (continued). "A significant difference in total PAX3 mRNA levels was observed between groups (p = 0.035), with PAX3 mRNA significantly higher in melanocytes than in melanoma, either primary (p = 0.001) or metastatic melanoma cell lines (p = 0.002)." (PMID 25880082, 2015). "RT-qPCR analysis of PAX3 expression in melanocytes and melanoma cells revealed significantly higher expression of the overall PAX3 mRNA in melanocytes compared to any of the melanoma cell lines analysed." (PMID 25880082, 2015). "In order to assess the mechanism behind this differential regulation, transcript expression profiles of PAX3 and post-translational modifications of the PAX3 protein were analysed in melanoma cells compared to normal melanocytes." (PMID 25880082, 2015). "The contribution of PAX3 (paired box 3) to MITF expression represents another melanoma-specific mechanism." (PMID 25433395, 2015). "We show that PAX3 differentially regulates various downstream target genes involved in cell proliferation in melanoma cells compared to melanocytes." (PMID 25880082, 2015). "By contrast, in the WM115 melanoma cell line, even though PAX3 mRNA levels are low (compared to melanocytes), the complete lack of MITF can result in lack of translational interference though miR-211, allowing PAX3 protein translation." (PMID 25880082, 2015). "Here we assessed the effects of PAX3 down-regulation on this panel of target genes in primary melanocytes versus melanoma cells." (PMID 25880082, 2015). "Similar levels of PAX3 protein were observed in all melanoma cell lines and in melanocytes (p = 0.088)." (PMID 25880082, 2015). "PAX3 is also highly expressed in melanoma, where it has been shown to contribute to cell survival, differentiation, migration and proliferation." (PMID 25880082, 2015). "Although PAX3 was found to be post-translationally modified, there was no qualitative difference in phosphorylation and ubiquitination between melanocytes and melanoma cells, while acetylation of PAX3 was reduced in melanoma cells." (PMID 25880082, 2015). "Through the use of a PAX3 knockdown experiment, we here confirm that PAX3 differentially regulates a number of these downstream targets in melanoma cells compared to normal melanocytes." (PMID 25880082, 2015). "CTC assessment with three markers—MART-1, MAGE-A3, and PAX3—provided prognostic discrimination before and during adjuvant treatment for resected stage IV melanoma patients." (PMID 24743024, 2014). "Reduction in PAX3 transcripts in melanoma cell lines induces increased cell detachment and a rise in cell death from apoptosis 16,22." (PMID 24188742, 2014). "This is consistent with a previous study showing that PAX3 knock-down induced G1 cell cycle arrest in B16 melanoma cells." (PMID 24188742, 2014). "Lastly, we show that the morphological effects of knocking down PAX3 versus MITF in melanoma cells differ." (PMID 24062982, 2013). "In melanoma, PAX3 expression is evident at all stages of disease progression, including the primary lesion, circulating melanoma cells, and metastatic lesions." (PMID 24069584, 2013). "PAX3-mediated regulation of melanoma cell survival and proliferation is through BCL2L1 and PTEN, and TPD52 (tumor protein D52) respectively." (PMID 24069584, 2013). "A similar role is suspected in melanoma cells, where PAX3 has been found to directly target the TGFβ promoter in metastatic melanoma cell lines." (PMID 24069584, 2013). "Consistent with its crucial roles in normal melanocytes and melanoma cells, PAX3 appears to be expressed on similar percentages of circulating tumor cells (CTCs) in patients with different stages of metastatic disease (AJCC stages 0–V)." (PMID 24069584, 2013). "Knock down of PAX3 induced increased cell detachment, growth reduction, and increased apoptosis in melanoma cell lines." (PMID 24069584, 2013). "Most recently, PAX3 has been identified as the mediator of anti-senescence and induced drug resistance in melanoma cells." (PMID 24069584, 2013).
melanoma (continued). "From these studies it is evident that PAX3 is involved in melanoma progression on multiple levels, and it is likely that at different stages of disease progression, PAX3 plays different roles." (PMID 24069584, 2013). "PAX3 is expressed in melanoma tissues and cell lines, melanocyte cell lines, and circulating melanoma cells." (PMID 24062982, 2013). "By controlling crucial cell processes (proliferation, cell survival, and migration), as well as promoting a less differentiated stem-like phenotype, PAX3 “ticks all the boxes” as an intrinsic factor driving melanoma development and progression." (PMID 24069584, 2013). "Co-localization of Ki67 with PAX3 was also relatively infrequent in melanomas including superficial spreading, lentigo maligna melanoma and nodular melanoma, and MMs, with an average of only ∼20% of cells co-expressing Ki67 and PAX3 in the latter." (PMID 24062982, 2013). "Knockdown of PAX3 expression in melanoma cells leads to reduced or arrested cell growth, and the induction of apoptosis and/or senescence." (PMID 24062982, 2013). "As expected, luciferase activation was higher in melanoma than in HeLa cells due to the cooperation of melanocyte specific components (Sox10 and Pax3), cAMP signaling machinery and the physiological tissue-specific expression of the M-Mitf promoter." (PMID 22427932, 2012). "PAX3 has also been recognized as an immunogenic protein in melanomas, inducing host immune response against PAX3-expressing tumor cells, resulting in suppression of tumor growth." (PMID 23285167, 2012). "On the flip side, PAX3 over expression occurs in many neural crest or neuroectodermal tumors such as melanoma, neuroblastoma, and Ewing's sarcoma." (PMID 22216266, 2011). "In melanocytes and melanoma it has been shown, that PAX3 is critical for the normal development of melanocytes, but plays also important roles during melanoma progression." (PMID 21876729, 2011). "In melanoma patients PAX3 has been identified as a significant marker for melanoma staging and for the detection of circulating melanoma cells." (PMID 21876729, 2011). "Samples of melanoma metastases showed MCAM expression in the majority (93.2%) of PAX3-positive cells." (PMID 20421967, 2010). "The tumors were strongly and diffusely positive for S100 and expressed the melanocyte markers tyrosinase, Dct, Pax3, and silver, consistent with a diagnosis of melanoma." (PMID 20141835, 2010). "A recent report from New Zealand shows PAX3 expression in all naevi, melanomas and normal skin samples, confirming our findings." (PMID 20421967, 2010). "Both naevi and primary melanoma samples show similar numbers of MITF-positive cells that also express PAX3 (97.2% and 94.5%, respectively)." (PMID 20421967, 2010). "The highest levels of PAX3 expression were found in melanoma metastases (mean fold change of 2583±1198), followed by naevi and primary melanomas with 101±39 and 73±55- fold change, respectively." (PMID 20421967, 2010). "This indicates that some PAX3-positive cells in naevi and melanomas have the capability to undergo vertical spread/migration." (PMID 20421967, 2010). "The observed frequency of PAX3 expression in naevi, melanomas and specifically in melanocytes in normal skin is much higher than reported elsewhere." (PMID 20421967, 2010). "Compared to naevi, primary melanomas showed MCAM expression in a larger proportion of PAX3-positive cells, 56.4%, which are again primarily located in the dermal component of the lesion." (PMID 20421967, 2010). "The majority of PAX3-positive cells in melanomas, naevi and normal skin co-express BCL2L2 at a similar frequency." (PMID 20421967, 2010). "In order to validate PAX3 expression in naevi and melanomas as well as to confirm that PAX3-positive cells in normal skin are in fact melanocytes, co-staining of PAX3 and MITF was assessed by immunofluorescence." (PMID 20421967, 2010).
melanoma (continued). "PAX3 expression was analysed by immunohistochemistry in tissue sections from paraffin embedded samples of normal skin, naevus, primary melanoma and melanoma metastases." (PMID 20421967, 2010). "In agreement with previous reports, we confirm here that PAX3 is expressed in all melanoma and naevi samples analysed." (PMID 20421967, 2010). "In summary, in addition to detection in the majority of naevus and melanoma cells, we conclusively show PAX3 expression in melanocytes of normal skin." (PMID 20421967, 2010). "Our results confirm co-expression of PAX3 and MCAM in melanomas and naevi, mainly in the cells that form nests located in the dermal component of the lesion, with melanoma samples showing larger numbers of PAX3, MCAM-positive cells compared to naevi." (PMID 20421967, 2010). "PAX3 expression was detected in all naevi (5/5), primary melanomas (5/5) and melanoma metastases analysed (5/5), and in one out of two (1/2) normal skin samples." (PMID 20421967, 2010). "It has also been identified as an immunogenic protein in melanomas, with several epitopes able to induce the host's immune response - stimulation of the immune response against PAX3-expressing tumour cells results in tumour growth suppression." (PMID 20421967, 2010). "In contrast, melanoma metastases have an overall low level of PAX3 expression and these cells were mainly located at the periphery of the lesion." (PMID 20421967, 2010). "Additional analysis by quantitative RT-PCR was performed on a separate set of samples, to confirm PAX3 expression in normal skin, naevi, primary melanomas, and melanoma metastases." (PMID 20421967, 2010). "We have chosen pathway-representative markers that are also downstream targets of PAX3 and analysed their co-expression with PAX3 in normal skin melanocytes, naevi and melanomas." (PMID 20421967, 2010). "In fact, PAX3 has been identified as a significant marker for melanoma staging and for detection of circulating melanoma cells." (PMID 20421967, 2010). "Double immunofluorescence staining of conjunctival melanoma paraffin sections demonstrated that all PAX3+ cells (green, arrows) co-expressed the melanocyte marker Melan-A (red), and the intensity of Melan-A staining was notably higher in the melanoma tissues relative to healthy tissues." (PMID 40216818, 2025). "The overexpression of PAX3 in melanoma is not purely an artifact of a prior initiating event of downstream effector genes, since the loss of PAX3 is catastrophic to melanoma viability regardless of expression of these downstream factors." (PMID 40428399, 2025). "Notably, PAX3 was significantly upregulated in conjunctival/limbal melanoma tissues compared to healthy counterparts, with expression co-localizing with melanocyte markers (Melan-A, HMB45, SOX10) and the proliferation marker Ki-67 in melanoma cells." (PMID 40216818, 2025). "Notably, while PAX3+ melanocytes in healthy tissues did not express the proliferation marker Ki-67 (arrows, red), the PAX3 + cells within the melanoma tissues stained positive for Ki-67 (arrowheads), indicative of their proliferative status." (PMID 40216818, 2025). "Interestingly, recent studies demonstrated activity of YK-4-279 against critical ETS1/PAX3 interactions in melanoma." (PMID 39448867, 2025). "What genes and enhancer elements are controlled by PAX3 in melanoma is not well understood." (PMID 40428399, 2025). "In neural crest, melanocyte, and melanoma cells, PAX3 was found to regulate MITF, NGN2, RET, SOSTDC1, MSX2, DCT, and TYRP1 genes, as well as genes expressed ubiquitously or widely (and including melanocytes), such as BCL-XL, CXCR4, FGFR4, HES1, MET, NF1, TGFb2, and WNT1." (PMID 40428399, 2025). "To address this, we performed CUT&RUN to reveal the cistrome of PAX3 in SK-MEL-5 melanoma cells." (PMID 40428399, 2025). "This analysis uncovered a clear cistromic map of PAX3 regulation in SK-MEL-5 melanoma cells." (PMID 40428399, 2025).